MAP3K5 (mitogen-activated protein kinase kinase kinase 5)
Diseases named in the same sentence as MAP3K5 in open-access papers (continued):
Sharing a sentence is not in itself a finding about the gene and the disease.
endothelial dysfunction (2 papers, 2014 to 2022). In vascular diseases, endothelial dysfunction is a systemic pathological state of the endothelium (the inner lining of blood vessels) and can be broadly defined as an imbalance between vasodilating and vasoconstricting substances produced by (or acting on) the endothelium. "Cellular stress mediators, such as mitogen-activated protein kinase kinase kinase 5 (MAP3K5) are highly expressed by epicardial adipocytes leading to cellular apoptosis and further endothelial dysfunction." (PMID 35784958, 2022).
liposarcoma (2 papers, 2010 to 2015). A usually painless malignant tumor that arises from adipose tissue. "Chromosomal imbalances additionally to the 12q13-q15 amplicon, including amplifications in 1p32 (including JUN), 1q21-q24, and/or 6q23 (including the ASK1 or MAP3K5 gene), have been reported to be more frequent in dedifferentiated liposarcoma than in well-differentiated liposarcoma." (PMID 25713799, 2015).
metastatic disease (2 papers, 2015 to 2023). "Similarly, patients whose tumors had high expression of DVL2 and MAP3K5 were more likely to progress to metastatic disease (log-rank P = 0.017 and P = 0.000083, respectively)." (PMID 37534375, 2023).
prostate tumor (2 papers, 2009 to 2019). "Given that mitochondria are a major source of reactive oxygen species (ROS), altered mitochondrial bioenergetics might induce MAP3K5 over-expression and contribute to the malignant progression of prostate tumors." (PMID 20035634, 2009).
atopic asthma (1 paper, 2009). An asthma that is characterized by symptoms that are triggered by an allergic reaction caused by inhaled allergens such as dust mite allergen, pet dander, pollen and mold. "Another kinase MAP3K5 was also related to atopy as well as atopic asthma in this study." (PMID 19961619, 2009).
atopic dermatitis (1 paper, 2009). "A non-synonymous SNP in COL18A1, intronic variants in MAP3K5 and a polymorphism in COL29A1, previously related to atopic dermatitis, were also associated with atopy, but not consistently replicated." (PMID 19961619, 2009).
dopaminergic neuroblastoma (1 paper, 2025). A neuroblastoma associated with increased dopamine excretion. "Apoptosis signal-regulating kinase 1 (ASK1, also known as MAP3K5) induces apoptosis through the activation of p38 MAPK and JNK in human SH-SY5Y dopaminergic neuroblastoma cells exposed to 6-hydroxydopamine (6-OHDA)." (PMID 41189817, 2025).
Infertility (1 paper, 2022). "Mutations in Map7 have been associated with male sterility, but Map3k5 homozygote mice have been reported to be fertile, suggesting that the loss of the first exon of Map7 is affecting MAP7 protein function, resulting in the observed infertility in rhme affected males." (PMID 35296311, 2022).
prostate intraepithelial neoplasia (1 paper, 2009). A neoplastic proliferation of the epithelial cells that line the acini and the ducts of the prostate gland. "Of note, we also observed significant protein overexpression in prostate intraepithelial neoplasia (PIN) and in regions of inflammation (data not shown), which is in agreement with the described involvement of MAP3K5 with inflammation processes." (PMID 20035634, 2009).
rectal cancer (1 paper, 2023). A primary or metastatic malignant neoplasm that affects the rectum. "Consistent with the high expression level of MAP3K5 in the present study, MAP3K5 was highly expressed in rectal cancer compared to healthy tissues." (PMID 36837498, 2023).
rhabdomyosarcoma (1 paper, 2015). A rare aggressive malignant mesenchymal neoplasm arising from skeletal muscle. "Indeed, p21 prevents stress-induced apoptosis mediated by the JNK and p38 signaling pathways by binding to and inhibiting the activity of the MAP3K5 (ASK1; MEKK5) in human rhabdomyosarcoma cells and by binding to JNK kinases, further preventing their activation by upstream kinases." (PMID 25885043, 2015).
cancer (113 papers, 2009 to 2025). A tumor composed of atypical neoplastic, often pleomorphic cells that invade other tissues. "Known driver genes from the cancer gene census in which we identified missense mutations included MAP3K5 and NRAS (p.Q61K)." (PMID 26414517, 2016). "Additionally, MAP3K5 has been implicated in regulating apoptosis and oxidative stress responses in cancer cells, suggesting its potential tumor-suppressive functions in GC." (PMID 39901302, 2025). "Among the MAP3K family members, MAP3K1, MAP3K4, and MAP3K5 have garnered considerable attention in the context of GC due to their established roles in cancer biology and signaling pathways relevant to gastric tumorigenesis." (PMID 39901302, 2025). "The SNV percentage heatmap found that MAP3K5, STAT1, and MAP3K9 have the highest single-nucleotide mutation rates in pan-cancer." (PMID 36969076, 2023). "MAP3K5 has been known as an upstream protein of mitogen-activated protein kinase cascade signalling pathway and plays a vital tumour-suppressive role in many types of cancers." (PMID 38106991, 2023). "Both Igf1r and Map3k5 were related to cancer and metabolism." (PMID 31484384, 2019). "On the contrary, knockdown of MAP3K5, LURAP1L, BNIP3 and HMOX1 enhanced cancer cell migration." (PMID 36899330, 2023). "Both pS134-GR and expression of the MAPK-scaffolding molecule 14-3-3ζ were essential for a functionally intact p38 MAPK signaling pathway downstream of MAP3K5/ASK1, indicative of a feedforward signaling loop wherein self-perpetuated GR phosphorylation enables cancer cell autonomy." (PMID 32357907, 2020).
tumor (110 papers, 2009 to 2025). "Among the genes exhibiting altered expression levels, aqp1, map3k5, and fgf18 are highly expressed in tumor-associated blood vessels in several human tumors." (PMID 23929008, 2014). "Among the 130 up-regulated genes, those encoding E-cadherin, MAPK10, MAP3K5, and PAK3 have been confirmed to inhibit tumor proliferation or invasion." (PMID 28454092, 2017). "Accordingly, MAP3K5 may affect the tumor microenvironment of OS by regulating ROS and inflammation-related signaling pathways, thereby affecting the occurrence and prognosis of OS." (PMID 40070565, 2025). "MAP3K5 might be related to a better prognosis of a tumor by activating macrophages, which also needed further study to validate." (PMID 34188683, 2021). "Many of these genes, including those encoding bFGF, MAPK10, MAP3K5, IL1R2, E-cadherin, Ki67, Cyclin E1, beta-catenin, 14-3-3 protein T-cell (YWHAQ), integrin alpha-V (ITGAV), integrin alpha-10 (ITGA10), CDK6, PCNA, CDKN1A, and PAK3, are related to tumor metastasis and regulation of cell migration." (PMID 28454092, 2017). "Several immune-related genes were shared across tumor types, with seven genes (CASP3, F2RL1, CD22, RORC, PLA2G6, SYCP1, MAP3K5) common to all four histologies." (PMID 40621458, 2025). "In the protein level, the gene expression of HSP90AA1, NFKB2, PTK2 was upregulated in tumor tissues, and CLU, JAK2, MAP3K5, and S100B were downregulated in the normal tissues." (PMID 36323529, 2023). "We found that MAP2K6, MAP3K5, MAP3K9, MAP3K12, RPS6KA2, RPS6KA5, and STAT1 were lowly expressed in tumor tissues; However, NFKB1, RAC1, SHC1, and TRAF2 are highly expressed compared to normal tissues." (PMID 36969076, 2023). "In this investigation, it was observed that MAP3K1, MAP3K3, MAP3K5, MAP3K10, and MAP3K15 were upregulated in HCC tumor tissues, whereas MAP3K7, MAP3K8, MAP3K9, and MAP3K11 were downregulated in tumor tissues in GSE14520." (PMID 35311629, 2022). "The result of q-rtPCR showed that the mRNA expression levels of PTGS2, RRM2, AURKA, CAV1, MAP3K5, STEAPS are higher in tumor samples and lower in normal tissue samples and the others had the reverse tendency." (PMID 33819918, 2021). "The results of protein interaction analysis in Pathway Common also showed that MAPK upstream kinases (MAP3K3, MAP3K5), ERBB3 and ULK1, which are important for tumor cell growth and proliferation, can bind to NEDD4L." (PMID 34539897, 2021). "Thus, when tumor cells experience cellular stress and/or when TGFβ1 is abundant in the TME, pS134-GR self-perpetuates its own phosphorylation by inducing the expression of MAP3K5 which in turn activates p38 MAPK in cooperation with 14-3-3ζ." (PMID 32357907, 2020).
infection (30 papers, 2012 to 2025). The state of being infected such as from the introduction of a foreign agent such as serum, vaccine, antigenic substance or organism. "A study indicated that genes encoding mitogen-activated protein kinase-kinase-kinase 5 (MAPKKK5) and CDPKs were upregulated after infection by rust." (PMID 36875570, 2023). "Upon infection with influenza virus, Map3k5−/− MEFs show decreased JNK and p38 activation and inhibited cell death." (PMID 27063938, 2016). "Then, we found that CGN, MAP3K5, GATA4 and RUNX1 related to tight junction were upregulated during DTMUV infection, indicating that these genes may play an important role in DTMUV entry." (PMID 35585616, 2022). "Overexpression of all the ISGs, except for MAP3K5 and IFI6 whose expression was cytotoxic in HUVEC VP30 cells, significantly reduced EBOV-driven luciferase expression at three days post infection in a similar manner of inhibition to that observed in HEK-293T VP30." (PMID 32528005, 2020). "Our microarray data revealed a major suppression of several components of the JNK pathway (MAP4K2, MAP3K5, MAP2K7 and MAP2K4), with the exception of JNK2 (also known as MAPK9), which was increased at 24 h; the other two Jun kinases, JNK1 and JNK3, were not significantly affected by infection." (PMID 28480889, 2017).
kidney disease (9 papers, 2018 to 2025). "To this end, we selected three MAP3K genes, Ask1 (Map3k5), Mlk2 (Map3k10), and Mlk3 (Map3k11), with connections to kidney disease for further analysis." (PMID 34962918, 2021). "Additionally, members of the MAP3K family, such as MAP3K5 (ASK1) and MAP3K14 (NIK), are known to be important in kidney disease, suggesting that modulating MAP3K11 activity could be a promising therapeutic strategy." (PMID 38892221, 2024).
neurological diseases (6 papers, 2019 to 2023). "Current drugs targeting MAP3K5 were not tested in neurological disease." (PMID 35837482, 2022).
MAP3K5 also shares sentences with these, for which no sentence is quoted: liver fibrosis (29 papers); Hepatic steatosis (23); neurodegenerative disease (19); non-alcoholic steatohepatitis (19); diabetic kidney disease (17); hepatocellular carcinoma (15); Cerebral ischemia (14); ischemia (14); Parkinson disease (11); steatosis (10); cervical cancer (9); Hyperglycemia (9); ischemic stroke (9); Stroke (9); cardiovascular diseases (8); Cognitive impairment (8); metabolic disorders (8); ovarian carcinoma (8); type 2 diabetes (8); amyotrophic lateral sclerosis (7); cardiac diseases (7); depression (7); pulmonary arterial hypertension (7); rheumatoid arthritis (7); atherosclerosis (6); colorectal cancer (6); fibrosis (6); glioma (6); liver diseases (6); lung adenocarcinoma (6).
A further 153 diseases each share a sentence with MAP3K5 in 6 papers or fewer.